TRIM21 (tripartite motif containing 21)
Diseases named in the same sentence as TRIM21 in open-access papers (continued):
Sharing a sentence is not in itself a finding about the gene and the disease.
infection (continued). "Previous experiments have shown that when TRIM21 binds to antibody-coated virus it blocks infection by mediating proteasomal-degradation of the virion." (PMID 37061529, 2023). "Generally speaking, TRIM21 is mainly involved in the antiviral response, during the infection, TRIM21 intercepts a virus by linking antigens that recognized by Fc-mediated antibody recognition to the ubiquitin, proteasome, and autophagy clearance mechanisms." (PMID 36159815, 2022). "The opacity increased as the infection progressed from day 7 to day 30 pi, with significant differences comparing the TRIM21+/− and TRIM21 KO at day 7 to day 30 pi." (PMID 35336995, 2022). "In the present study, we found local HSV-1-induced TRIM21 corneal expression during acute infection is temporal in nature returning to baseline levels by day 14 pi." (PMID 35336995, 2022). "RT-qPCR results showed that at 24 h post-infection, ASFV B646L gene (encoding ASFV P72 structural protein) expression gradually increased with increasing VIM or TRIM21 transfection dose, but gradually decreased with TUFM." (PMID 36406406, 2022). "By binding IgM, TRIM21 provides protection from primary infections, and by binding IgG it can protect against secondary infection." (PMID 34552597, 2021). "IFN-γ inducible tripartite motif 21 (TRIM21), an E3 ligase, plays an important role in anti-infection responses against the intracellular pathogens including bacteria, virus, and parasite." (PMID 34124071, 2021). "Virus shedding by naïve mice on day 3 post-infection was comparable for both wild type and TRIM21 knockout mice, confirming that TRIM21 antiviral activity is antibody-dependent." (PMID 32750093, 2020). "TRIM21 has been shown to activate NF-κB upon infection with antibody-bound human adenovirus and rhinovirus, feline calicivirus, and Salmonella enterica." (PMID 32760166, 2020). "Our results demonstrated that HPV E7 interacted with the HINB domain of IFI16 and promoted the ubiquitin-proteasome-mediated degradation of IFI16 by recruiting the E3 ligase TRIM21, resulting in the inhibition of cell pyroptosis during infection." (PMID 33061806, 2020). "By 4 days post-infection the DLP-immunized TRIM21 knockout mice had controlled virus shedding to a similar degree to that of the wild type mice." (PMID 32750093, 2020). "An antibody-bound virus that escapes the endosomal compartment and enters the cytosol during infection will be met by TRIM21, which detects the virus by binding to the antibody Fc region." (PMID 32760166, 2020). "This indicates that TRIM21 plays a role in neutrophil recruitment and hence the inflammasome response during in vivo infection." (PMID 31468569, 2019). "The specific contribution of TRIM21 to immune signaling was determined by comparing the transcriptional changes in immune genes induced upon infection in WT vs. TRIM21 KO mice using rh9C12-WT vs. rh9C12-H433A." (PMID 31555278, 2019). "Upon infection, TRIM21 is derepressed by IKKβ and TANK-binding kinase 1 (TBK1)-mediated phosphorylation in the RING domain, promoting E2 binding, RING catalysis, NF-κB activation, and cytokine transcription." (PMID 31548319, 2019). "Upon infection of cells with Ad5-antibody complexes, TRIM21 mediates a sequential and coordinated effector and signaling response." (PMID 31555278, 2019). "In line with this, stimulation of cells with poly(I:C) or infection with antibody coated Ad5 resulted in TRIM21 phosphorylation." (PMID 31555278, 2019). "Following incubation with EHRL-4-opsonized E. chaffeensis, the cytoplasmic levels of NF-κB were increased at 2 to 6 h, and TRIM21 levels decreased at 30 min and 1 h postinfection relative to that with infection alone." (PMID 31548319, 2019). "EHRL-15 blocked E. chaffeensis entry, while EHRL-4 inhibited infection by engaging the intracellular cytosolic FcR TRIM21." (PMID 31548319, 2019).
infection (continued). "To separate the contributions of TRIM21 and complement to Ad5 neutralization, we compared 9C12-WT with the P329A mutant, which ablates C1q binding, and performed Ad5 infections in WT and TRIM21 KO mice." (PMID 30926239, 2019). "At the same time TRIM21 sends a signal to the cell’s nucleus to activate certain genes that protect cells across the body from subsequent infection." (PMID 29667579, 2018). "TRIM21 expression is significantly up-regulated in hearts of mice on day 3 post infection, and systemic TRIM21 effectively inhibits CVB3 replication in vivo." (PMID 30410495, 2018). "TRIM21 activation results in cytokine upregulation in mice within hours of infection and is a significant component of the inflammatory response induced by protective antibodies." (PMID 29667579, 2018). "Phosphorylation of S80 or its replacement by a phosphomimetic displaces the B-Box, allowing E2 recruitment and potentiating TRIM21 ubiquitination activity, NF-κB signalling and cytokine transcription upon infection with DNA or RNA viruses." (PMID 29667579, 2018). "To confirm the importance of S80 and B-Box inhibition in regulating TRIM21 immune signaling, we repeated our infection experiments using an unrelated RNA virus, human rhinovirus 14 (HRV)." (PMID 29667579, 2018). "To demonstrate the importance of TRIM21 phosphorylation in immune sensing during infection, we challenged cells expressing different TRIM21 mutants with human adenovirus (Adv) ± human serum IgG and measured TNFA transcription after 4 hr." (PMID 29667579, 2018). "We found that CVB3 infection up-regulated the expression of TRIM21 in hearts of mice and cardiomyocytes at early phase of infection." (PMID 30410495, 2018). "As with AdV, expression of wild-type TRIM21 in knockout cells increased TNFA induction upon infection with HRV + antibody." (PMID 29667579, 2018). "Further experiments then showed that this process helps regulate TRIM21 during infections with different viruses, including rhinovirus – the virus behind the common cold – and adenovirus – a common cause of respiratory infection." (PMID 29667579, 2018). "Upon infection of diverse cell types, TRIM21 triggers intracellular degradation of pathogens and innate immune signaling." (PMID 30233598, 2018). "TRIM21 knockout mice exhibited a higher clinical score (characterised by piloerection, hunching and reduced motility) from day 7 post-infection onwards." (PMID 28701773, 2017). "At 10 days post-infection, 77% of the TRIM21 knockout mice had succumbed to infection while 83% of the control mice had survived." (PMID 28701773, 2017). "We thus investigated by transmission electron microscopy the integrity of the vacuolar membrane of type II Toxoplasma in IFNγ-stimulated wild-type or TRIM21 knockout MEFs 2 h after infection." (PMID 28701773, 2017). "Based on our mass spectrometric analysis and the loss-of-function experiments in vitro, we infected Trim21-/- mice with LCMV strain Cl13 and found impaired virus control in the late phase of infection." (PMID 29261807, 2017). "This was in line with comparable viremia kinetics of Cl13 in Trim21-/- and WT mice during the early phase of infection." (PMID 29261807, 2017). "Viruses that traffic surface-bound antibodies into the cell during infection recruit TRIM21 via a high affinity interaction between Fc and TRIM21 PRYSPRY domain." (PMID 31558002, 2016). "Consistent with the neutralization data, h9C12 hexon binding mutants also provoked significantly reduced TRIM21-dependent NFκB activation during infection." (PMID 27881870, 2016). "In contrast, it is intuitive that virus-antibody complexes with slow off-rates will be more likely to persist during the infection process to engage with TRIM21 once they reach the cytosol." (PMID 27881870, 2016). "We demonstrate that TRIM21 enables the RNA sensor RIG-I to detect infection by an incoming RNA virus and the DNA sensor cGAS to detect infection by a DNA virus." (PMID 26506431, 2015).
infection (continued). "TRIM21 intercepts incoming antibody-opsonized virions during cellular infection, mediating efficient post-entry neutralization and innate immune signaling." (PMID 26506431, 2015). "TRIM21 participates in both naïve infection (through its ability to bind IgM) and secondary infection (by binding IgG)." (PMID 26506431, 2015). "The ability to intercept incoming virions allows TRIM21 to trigger an immune response during the early stages of cellular infection." (PMID 26506431, 2015). "A rapid inflammatory response was observed 6 hours post infection in the brain tissue of TRIM21+/+ animals that also received immune serum." (PMID 26506431, 2015). "JEV-infected CHME3 cells showed increased phosphorylation of IRF3 as compared to controls; however, silencing of TRIM21 prior to infection further enhanced the phosphorylation and activation of IRF3." (PMID 24485101, 2014). "E3 ubiquitin-protein ligase tripartite motif containing 21 (TRIM21) is a cytosolic antibody receptor that recognizes intracellular antibodies during infection." (PMID 25505465, 2014). "This is supported by the observation that the activation of IRF3 in JEV infection is further enhanced by knockdown of TRIM21 in CHME3 cells prior to infection." (PMID 24485101, 2014). "Here we investigate the antiviral activity of TRIM21 during infection of a replication-competent wild-type (WT) virus, mouse adenovirus type 1 (MAV-1)." (PMID 23596308, 2013). "In the presence of immune sera and upon infection, TRIM21 also activates a proinflammatory response, resulting in secretion of tumor necrosis factor alpha (TNF-α) and interleukin-6 (IL-6)." (PMID 23596308, 2013). "Here we show that TRIM21 potently inhibits the spreading infection of a replicating cytopathic virus and activates innate immunity." (PMID 23596308, 2013). "Considering that TRIM21 transcription was primarily upregulated in cells from individuals with mild symptoms and that this pathway may be protective against infection, we further investigated its downstream components only in this group of patients." (PMID 40141410, 2025). "We detected the expression of TRIM21 after DK/212 infection in A549 cells." (PMID 38542289, 2024). "Nonetheless, the anti-TRIM21 may yield positive results in serum samples from individuals with different infections or tumors." (PMID 39165359, 2024). "We show here that sera from CCHFV-exposed humans can inhibit CCHFV replication in our EDNA and inhibition is again enhanced by TRIM21 suggesting anti-NP antibodies that arise in humans during natural infection may contribute to control of the virus." (PMID 39455551, 2024). "In combining this with previous results, we believe that DK/212 infection enhances the expression of TRIM21 and competitively binds to SQSTM1 to reduce the release of NRF2 from the KEAP1-NRF2 complex, which ultimately destroys the antioxidant system of cells and promotes ferroptosis." (PMID 38542289, 2024). "Thereby, our data demonstrated that TRIM21 is a host restriction factor of infection by certain IAV subtypes, implying that TRIM21 may be a factor that influences the host adaption of IAV." (PMID 37343022, 2023). "First, we performed RNA immunoprecipitation (RIP) analysis to explore whether TRIM21 affects PKR binding to viral RNA in HEK293T cells after infection with VSV." (PMID 37327222, 2023). "Furthermore, TRIM21 can regulate the expression of IFN by feedback, but the mechanism of TRIM21 regulating IFN is different in different virus-infection processes." (PMID 35062360, 2022). "In brief, our research identified that in human cells, IFN-γ-inducible TRIM21 functioned in the innate immune responses against type III T. gondii infection; however, TgROP18I promoted TRIM21 phosphorylation, leading to TRIM21 degradation for immune escape in type I strain infection." (PMID 34124071, 2021).
infection (continued). "TRIM21 acts as an important factor involved in the innate immune responses against microbial infection, including bacterial, viral, and parasite, however, little about TRIM21 is known for parasites infection." (PMID 34124071, 2021). "Only in TRIM21‐reconstituted cells did electroporation of anti‐N sera reduce infection." (PMID 34323299, 2021). "To establish whether activity in the polyclonal sera is dependent upon TRIM21, we compared infection in 293T TRIM21 KO ACE2 cells reconstituted with either empty vector or TRIM21." (PMID 34323299, 2021). "To assess whether upregulated TRIM21 can be reversed by TgROP18I during RH infection, we conducted a proliferation assay with RH-△rop18 and CEP-rop18I strains." (PMID 34124071, 2021). "Comparing to RH-△rop18 infection, RH infection led to a significant degradation of TRIM21." (PMID 34124071, 2021). "The interception of incoming antibody‐coated AdV during macrophage infection suggested that in addition to stimulating the inflammasome TRIM21 might operate to protect these cells from becoming a niche for viral replication." (PMID 31468569, 2019). "Interestingly, the fact that naive mice demonstrate TRIM21 dependent protection suggests that the early antibody response, likely in the form of IgM, works with TRIM21 in vivo to prevent infection." (PMID 31555278, 2019). "Also, use of the fully replicative MAV-1 demonstrates that TRIM21 is effective during an active spreading infection." (PMID 31555278, 2019). "We therefore also tested whether our bespoke native-promoter driven system properly recapitulates the ability of TRIM21 to detect incoming antibody-coated virions during infection." (PMID 31613747, 2019). "Finally, we monitored changes in TRIM21 phosphorylation following infection with antibody-coated adenovirus, under conditions where we have previously demonstrated TRIM21-dependent antiviral activity." (PMID 29667579, 2018). "Upon infection, antibody-coated pathogens are detected in the cytosol by TRIM21." (PMID 29667579, 2018). "TRIM21 protects cells from pathogen infection by stimulating a dual effector and sensor response." (PMID 29667579, 2018). "Similar antiviral effects of TRIM21 were observed upon infection with ARM WT." (PMID 29261807, 2017). "Interestingly, Trim21-/- and WT mice showed comparable levels of viremia in the early stage of infection but approximately two weeks after infection Trim21-/- mice exhibited impaired control of Cl13 in the blood compared to WT mice (p-value <0.0001)." (PMID 29261807, 2017). "TRIM21 was first demonstrated to interact with IgG1 Fc domain in a yeast two-hybrid screen but the significance of this interaction remained cryptic until adenovirus particles were demonstrated to import antibodies during infection." (PMID 31558002, 2016). "Cytoplasmic nucleic acid sensors are able to detect the genomes that are released following TRIM21 neutralization, stimulating a wave of cytokine transcription at around 8 h post-infection that is distinct from initial detection by TRIM21, which peaks at around 4 h post-infection." (PMID 31558002, 2016). "During infection with rotavirus, antibodies that are attached to the viral capsid may be carried into the cytosolic compartment of infected cells and recognized by TRIM21 targeting the virus for proteasomal degradation." (PMID 27439689, 2016). "The relative insensitivity of TRIM21 function to antibody:antigen on-rate may reflect the fact that activity is triggered primarily by the infection of pre-formed virus-antibody complexes." (PMID 27881870, 2016). "Upon infection with either the DNA virus adenovirus or the RNA virus rhinovirus we observed two early waves of innate immune signaling, both of which were dependent on TRIM21." (PMID 26506431, 2015). "Interestingly, the Ub-ligase activity of TRIM21, in addition to target viruses for destruction, also alerts the body to infection." (PMID 25278942, 2014).
infection (continued). "However, overexpression of TRIM21 prior to infection resulted in a reduction of p-IRF3 levels post infection compared to the CHME3 cells only infected with JEV without TRIM21 transfection." (PMID 24485101, 2014). "Finally, we have found that TRIM21 is important in inducing proinflammatory cytokine production upon infection with MAV-1." (PMID 23596308, 2013). "If as few as 10% of the cells were equipped with all receptor signaling components, and considering the total number of cells in normal lungs as a reference, we would find at least 2.3 × 109 cells per individual who could respond to the infection through TRIM21." (PMID 40141410, 2025). "Therefore, it might be reasonable to investigate TRIM21 protein levels at different time points post-infection." (PMID 38977311, 2024). "In addition, another group found that TRIM21 can inhibit HBV replication by directly triggering the K48-linked polyubiquitination, followed by proteasome degradation of viral HBx protein in the early step of the infection." (PMID 36675197, 2023). "Importantly, we demonstrated that anti-L1 antibody-bound HPV16 PsV were capable of eliciting the up-regulation of TRIM21 expression by HEK 293FT cells and, therefore may represent one protective response of TRIM21 against intracellular infection of HPV16 PsV." (PMID 35619167, 2022). "Similarly, infection in the presence of the Ad5 hexon specific mouse-human chimeric rh9C12 antibody resulted in more than 700 differentially expressed genes between WT and TRIM21 KO mice." (PMID 31555278, 2019). "It is still unknown how TRIM21 is precisely regulated and only activated during an infection." (PMID 30675393, 2019). "Thus, the complement system and TRIM21 may work in concert to prevent infection but also to block Ad5 based gene delivery." (PMID 31555278, 2019). "Of the two mechanisms of antibody‐induced inflammasome activation we describe here, we speculate that TRIM21 might be more important at the earlier stages of infection where antibody occupancy on each virion is low and most viruses enter the cell via a natural infectious route." (PMID 31468569, 2019). "Thus, JEV could exploit TRIM21 to attenuate host antiviral innate immune response during the early stage of infection." (PMID 27667714, 2016). "However, TRIM21 neutralization provokes the catastrophic destruction of virus particles that prevents the coordinated uncoating events that must occur for productive infection." (PMID 31558002, 2016). "Finally, we tested whether the ability of TRIM21 to promote immune activation prior to viral replication facilitates a rapid inflammatory response during infection in vivo." (PMID 26506431, 2015). "Thus, while TRIM21 may provide crucial antiviral protection, its role in preventing a spreading infection remained to be evaluated." (PMID 23596308, 2013). "Together, these data suggest that NP-specific antibody, elicited by vaccination or natural infection can inhibit CCHFV replication if present in the cytoplasm of infected cells and that this inhibition is potentiated by TRIM21." (PMID 39455551, 2024). "The expression of TRIM21, MDA5, cGAS, LGP2, and IFI44 was increased and the expression of RAS, GLOM2, HSP, FOX and TLCD4B was decreased in the foregut following SVCV infection." (PMID 36330521, 2022). "These genes, especially for PVLR1, TRIM21, and TRIM29, are strongly related to immune responses to infection, which are warranted for further cellular and animal studies." (PMID 36353114, 2022). "Thereafter, TRIM21-KO and TRIM21-OE were infected with PCV2 for 24, 48, or 72 h, and the infection of PCV2 was evaluated." (PMID 35062360, 2022). "It has been previously shown that TRIM21 uses anti-N antibodies to degrade the nucleoprotein of LCMV, promote cytotoxic T-cells and clear mice of infection." (PMID 34867975, 2021).